RN7SKP59 (RN7SK pseudogene 59)
Gene: Miscellaneous RNA gene on chromosome 9 (78,165,465 to 78,165,778, forward strand). Ensembl gene ENSG00000222452.
Homologues: Orthologues: chimpanzee 7SK (88% identical), mouse Gm55029 (52% identical), mouse Gm56292 (46% identical). Paralogues in human: RN7SKP58 (75% identical), RN7SKP255 (69% identical), RN7SKP79 (69% identical), RN7SKP180 (68% identical), RN7SKP189 (68% identical), RN7SKP6 (68% identical), RN7SKP78 (68% identical), RN7SKP9 (68% identical), 7SK (67% identical), RN7SKP171 (67% identical), RN7SKP250 (67% identical), RN7SKP128 (67% identical), and 284 more.